TNF (tumor necrosis factor)
Diseases named in the same sentence as TNF in open-access papers (continued):
Sharing a sentence is not in itself a finding about the gene and the disease.
tumor (continued). "As an antagonist of IAP, birinapant inhibits IAP to sensitize tumor cells to CAR-T cell-derived TNF and significantly enhances the anti-tumor activity of CAR-T lymphocyte therapy in vitro and in vivo." (PMID 39253578, 2024). "The incorporation of CPP significantly enhanced the binding of TNF-α to its receptor, while SPIONs facilitated the localization of EVs to the tumor site under magnetic field, thereby improving the targeting efficiency." (PMID 38164177, 2024). "TNF-α is involved in inflammation and has a dual function in cancer as an inductor of metastasis or in tumor elimination." (PMID 39126001, 2024). "These transcription factors lead to the secretion of pro-inflammatory cytokines, including TNF-α, IL-1β, and IL-6, which further promote tumor growth." (PMID 39267826, 2024). "Subsequent investigations have revealed its identity as a circulating factor induced by bacteria, possessing potent anti-tumor activity and referred to as TNF." (PMID 38835752, 2024). "We show JHU083-mediated glutamine antagonism in tumor microenvironments induced by TNF, proinflammatory, and mTORC1 signaling in intratumoral TAM clusters." (PMID 38701369, 2024). "Deacetylated KLF5 promoted tumor cells to secrete TNF-α, which stimulated inflammatory CAFs to release FGF9." (PMID 38781024, 2024). "The anti-tumoral N1 phenotype has been associated with an upregulation of TNF, which promotes TAN priming for ROS release in order to enhance tumor cell death." (PMID 37444436, 2023). "Coculture of BTICs with tumor reactive cytotoxic T cells or with T cell-derived factors induced TSPO up-regulation through T cell derived TNFα and IFNγ." (PMID 37158962, 2023). "With further research, NETs have been shown to induce many pro-inflammatory factors in tumor microenvironment, like IL-8, TNF, and PDL1, during the regulation of cancer." (PMID 37153547, 2023). "The strong antibody response in this patient, together with their cellular responses, reflected by high Th1 cytokine (IFNγ/IL-10, and TNFα/IL-10) ratios, correlated with the patient’s increase in progression-free survival and tumor reduction." (PMID 38203458, 2023). "TNF-α, for instance, is able to kill tumor cells in a dose-dependent manner but only if TNFR1 is expressed on the target cells." (PMID 37587450, 2023). "Previous studies showed that GJs activated STING signaling pathways and elevated the levels of IFN-a and TNF cytokines, promoting tumor cell growth and chemoresistance." (PMID 37554265, 2023). "In this study, we focused on interleukin (IL)-6, soluble IL-2 receptor (sIL-2R) and tumor necrosis factor (TNF)-α as cytokines related to tumor immunity and microenvironment." (PMID 37733188, 2023). "Unfortunately, TNF-α can also inhibit the anti-tumor response and decrease the visibility of tumor cells to surrounding immune cells." (PMID 37514190, 2023). "Another strategy to induce vascular normalization is in situ delivery of angiostatic factors such as tumor necrosis factor alpha (TNFα), which at low doses can stabilize the tumor vasculature and improve vascular permeability." (PMID 37727791, 2023). "The relative staining intensity quantification also demonstrated that P70 expression approximated TNF-α expression levels in all types of PCa tissue samples, including normal, tumor, and adjacent tissues." (PMID 37867861, 2023). "Circulating chemokines such as tumor necrosis factor (TNF) and interleukin (IL)-1 can influence the surrounding tumor tissue." (PMID 37965463, 2023). "We next examined and found that the positive staining of the cytotoxic molecules IFN-γ and TNF (typical markers for effector T-cell persistence) in tumor-infiltrating CD8+ T cells were increased in KO mice compared with WT mice." (PMID 38071226, 2023).
tumor (continued). "The results showed that TCL1A+ B cells from SD patients are more likely to be enriched in hypoxia, NFAT, and TNF-alpha pathways, correlated with tumor invasion and metastasis, indicating a pro-tumoral environment." (PMID 37791059, 2023). "In BALB/C mice with implanted WEHI-164 cells L19-mTNF, an immunocytokine consisting of L19 antibody fragment and murine TNF-α demonstrated mild tumor growth inhibition as a single agent, with complete response in one of four animals." (PMID 36839658, 2023). "The production of IFN‐γ and TNF‐α by tumor‐infiltrating OT1 CD8+ T cells was higher in Tipe2ΔNK/ΔNK OT1 mice than in control OT1 mice." (PMID 36807566, 2023). "In the tumor inflammatory microenvironment, hMSC polarization can be achieved following the release of TNF-α and INF-γ from activated T cells." (PMID 36814921, 2023). "TNF can also exhibit various antitumor effects, such as the induction of tumor cell apoptosis, and the recruitment and activation of tumor-reactive T cells." (PMID 36817127, 2023). "We found significant differences in the NF-κB p65 (RelA) and TNFα gene expression profiles between tumor and matched normal tissues using the TCGA database, which contained total unique analyses of about 163 tumor and 207 normal tissue samples." (PMID 37892820, 2023). "Taken together, our data suggest that CD4 CTLs can mount specific, HLA-II-restricted killing of HT-29 tumor cells via the perforin and TNFα pathways." (PMID 37185301, 2023). "Macrophages are also activated by damage-associated molecular patterns such as ATP, HMGB1, histone H3, and other signals through Toll-like receptors resulting from tumor and surrounding cell death, and macrophages will, in turn, further release IL-6 and TNF-α." (PMID 36970518, 2023). "Then the ensuing activation of STING promotes the secretion of TNF-α, a member of the TNF/TNFR cytokine superfamily from astrocytes involved in tumor metastasis." (PMID 37122745, 2023). "These, in turn, produce tumor necrosis factor-alpha (TNF-α) and nitric oxide (NO•) that amplify the migration of macrophages to the tumor site." (PMID 37888647, 2023). "Activated CAR-T cells release IFN-γ, TNF-α, and GM-CSF, which are cytotoxic on tumor cells but will also activate myeloid cells." (PMID 36970518, 2023). "During the burn-induced inflammatory response, pro-inflammatory cytokines such as IL-6, IL-8, tumor TNF-α, and anti-inflammatory cytokines such as IL-10 are released." (PMID 37090725, 2023). "We find that tumours with high‐IP expression exhibit cytotoxic immune cell infiltration and upregulation of IFN‐γ and TNF‐α pathways in tumour cells." (PMID 37097039, 2023). "We established a xenograft tumor model with HGC-27 cells treated with TNF+ Treg/TNF- Treg supernatant in NVSG mice by subcutaneous injection." (PMID 37534250, 2023). "TNF is a cytokine that has three main effects: antiangiogenic (acting on the endothelial cells of the tumor vasculature), stimulation of the immune response, and direct toxicity mediated by apoptosis." (PMID 38138884, 2023). "Luteolin has been demonstrated that it exerted significant tumor suppressive activity on several cancers, by suppressing the secretion of IL-6, IL-12 and TNF-α in macrophages." (PMID 37560476, 2023). "Strikingly, we found increased IFN-γ+ and double-positive IFN-γ+ and TNF-α+ tumor-infiltrating CD8+ and CD4+ T cells in tumors with B7-H3 knockdown compared with controls." (PMID 36869048, 2023). "This is performed by reducing tumor growth and inflammatory cytokine secretion (IL-6,-8, TNF-α), activating pro-apoptotic molecules, reducing glycolysis proteins, regulating impaired metabolism and immune responses, or preserving skeletal muscle mass." (PMID 36829437, 2023). "Our phage gene delivery particle is designed to deliver the TNFα cytokine into the tumor microenvironment to ensure a local and dual selective effect on both the tumor microvasculature and tumor cells." (PMID 37331004, 2023).
tumor (continued). "Murine models show that TRM cells delay tumor progression by releasing cytokines (Interferons and TNFα) that attract other immune cells into the tumor microenvironment." (PMID 37426662, 2023). "Regarding tumor-specific responses, Th1 and Th2 cells and their related cytokines, including IFN-γ, TNF-α, and IL-4, are mostly considered anti-tumor elements." (PMID 38137433, 2023). "CEMIP induces endothelial cells and inflammation in perivascular niches and promotes tumor brain metastasis by upregulating pro‐inflammatory cytokine tumor necrosis factor (TNF), prostaglandin–endoperoxide synthase 2 (PTGS2), and CCL/CXCL." (PMID 37902101, 2023). "The development of a large tumor coincides with occupation of a state showing notable production of TNF-α." (PMID 37043573, 2023). "Meanwhile, ClyA promoted the expression of pro-inflammatory cytokines IL-1β and TNF-α at tumor sites." (PMID 37896250, 2023). "In small concentrations, TNF acts as a tumor stimulator, increasing reactive oxygen species and promoting DNA damage and mutations." (PMID 37046608, 2023). "TNFα acts on tumor growth and macrophage proliferation in CRC cells, and subcutaneous transplantation of CRC cells suppresses the expression of TNFα, resulting in a reduction in the size of tumor and the number of macrophages." (PMID 36996146, 2023). "Consistent with the preceding findings, IFNγ secretion was increased both in the primary and the rechallenged tumor rejective responses, and serum TNFα level was increased significantly during tumor rechallenge." (PMID 37407600, 2023). "TSPO upregulation in the tumor cells required antigen specific activation of T cells interacting with the tumor cells and was initiated through IFNγ and TNFα secreted by activated T cells." (PMID 37158962, 2023). "We postulated targeted gene delivery for selective production of TNFα in the tumor microenvironment as a solution to reduce systemic toxicity and control the time window of TNFα bioavailability." (PMID 37331004, 2023). "The administration of TNF antiserum partially reversed the tumor-induced reduction in rodent food intake." (PMID 37383489, 2023). "For a typical BRAFV600E-driven tumor, the model exhibits two steady states, one with the TNF-α feedback loop engaged and the other with it turned off, as expected." (PMID 37043573, 2023). "TNF-α has multiple functions, such as induction of adaptive immunity, cell apoptosis, proliferation, and inhibition of tumor cell growth." (PMID 37630849, 2023). "Tumor necrosis factor-alpha (TNF-α) is involved in tumor growth, angiogenesis and metastasis in EAC model." (PMID 37507468, 2023). "Based on the available data, DEX seems to have beneficial effects on the production of TNF-α and tumor progression." (PMID 36765695, 2023). "Studies in a rat model of CRC demonstrated that (3R)-falcarinol and (3R,8S)-falcarindiol, isolated from carrots selectively, inhibited the expression of COX-2 in tumor tissue as well as TNF-α and IL-6, thus explaining the CRC-preventive effect of carrots." (PMID 37894640, 2023). "Correspondingly, the inflammatory factors of IL-1β, TNF-α, and IL-6 were increased in the MD@SA hydrogel group, offering a robust immune environment to restrict tumor regrowth." (PMID 37981704, 2023). "Pathways of BP were associated with the regulation of tumor cell response, apoptosis pathway, cell cycle, tumor-related signaling pathway, and regulation of tumor necrosis factor." (PMID 37456238, 2023). "This positive feedback can produce chemotaxis of macrophages, and then produce TNF-α, resulting in increased IL-6 produced by tumor cells." (PMID 37151385, 2023). "Brief administration of TNF-α blockers effectively enhances the killing of tumor cells while reducing inflammation-induced neurotoxicity, enhancing viral replication and survival in GBM intracranial tumors." (PMID 37993941, 2023).
tumor (continued). "The suppression of NF-κB by anti-TNFα mAb inhibited the activity of antiapoptotic factors and promoted tumor apoptosis in a mouse liver model." (PMID 36996146, 2023). "The secretion of IFN-γ and TNF induces tumor cell growth arrest as well as the expression of ligands for the activating NK cell receptors, DNAM-1 and CRTAM, which initiate NK cell tumor surveillance." (PMID 37111458, 2023). "It induces powerful melanoma-specific CTL responses and reduces tumour immunosuppression by increasing TNF-α and IL-12 levels." (PMID 37514054, 2023). "In particular, the authors proposed that the MC-derived tumor necrosis factor α (TNFα) acts in an autocrine fashion to amplify the local MC pool at the site of the tumor’s formation and directly contributes to the adenomatous polyp growth." (PMID 36766801, 2023). "For example, TNF-α-based therapeutics activate apoptosis, inhibit tumor cell proliferation, and disrupt tumor vasculature, whereas IL-2- or IL-12-based molecules activate and enhance NK and T cells." (PMID 36839658, 2023). "The cytokines interleukin-6 (IL-6) and tumor necrosis factor-alpha (TNF-α) promote inflammation and tumor progression in CRPC13,14." (PMID 37646236, 2023). "IL-4, TGFβ and IL-8 were assessed in low amounts (471 to 820 pg/mg of tumor); CCL2, IL-12, IL-6 and IL-10 in moderate amounts (2825 to 3440 pg/mg of tumor); and IFNγ, TNFα, IL-1β and IL-2 in high amounts (6293 to 13,492 pg/mg of tumor)." (PMID 37526660, 2023). "It has been stated that TNF-α is involved in cell proliferation, tumor migration, tumor metastasis, matrix degradation, invasion, and angiogenesis." (PMID 37274025, 2023). "TNF-α can increase the permeability of the vascular lining of tumor cells, allowing drug permeation into tumor cells as well as infiltration of blood and immune cells leading to hemorrhagic necrosis." (PMID 37514190, 2023). "M1 macrophages elicit a response to cytokines, such as interferon-γ (IFN-γ), that impedes tumor progression by producing pro-inflammatory and immunostimulatory cytokines, including IL-12 and TNF-α." (PMID 37345095, 2023). "Nevertheless, Zhou et al42 revealed that PMN‐MDSCs were able to inhibit tumor infiltration of IFN‐γ+TNF‐α+CD8+ T lymphocytes through the expression of Arg‐1." (PMID 37326143, 2023). "As the primary immune cells, lymphocytes can stimulate the immune response in the tumor microenvironment and release tumor necrosis factor, interferon‐γ and other cytokines, producing antitumor effects." (PMID 37975152, 2023). "IFNγ and TNFα can stimulate or activate other anti-tumor immune responses (both adaptive and innate) and can promote antigen presentation, which supports tumor recognition and elimination." (PMID 36175673, 2023). "In a study of a cohort of patients with inflammatory breast cancer, a direct correlation between TNF-α production by peripheral blood T lymphocytes and the detection of circulating tumor cells expressing EMT markers was found." (PMID 37138170, 2023). "In this context, gemcitabine treatment has been shown to increase TNF-α mRNA expression in tumour cells." (PMID 37686338, 2023). "M1 macrophages exhibit anti-tumor activity and primarily inhibit tumor growth and metastasis by producing inflammatory mediators and cytokines, such as tumor necrosis factor-alpha (TNF-α), interleukin-12 (IL-12), and interleukin-6 (IL-6)." (PMID 38037023, 2023). "Our bioinformatic analysis showed that RNA expression of TNF-α is over-expressed in tumor tissues of DLBC patients." (PMID 37428723, 2023). "Tumour necrosis factor α (TNF‐α) promotes immune cell apoptosis in the tumour microenvironment, and TNF‐α expression is also reduced after CBS and CSE knockdown." (PMID 36929586, 2023). "We found that human IFN-γ and TNF-α serum levels were far higher in the DC/tumor fusion +LPS-Nb36 group versus those in the others." (PMID 37419930, 2023).
tumor (continued). "In this study, we found that diHEP-DPA significantly inhibited the infiltration of TAMs and decreased the secretion of MMP2, MMP9, VEGF, IL-6, and TNF-α in tumor tissue." (PMID 36827121, 2023). "In response to NF-κB actuation, cells in the tumor microenvironment secrete proinflammatory mediators, such as TNF-α and IL-1." (PMID 36891273, 2023). "In our previous study, the transcriptional level of KDM2A was increased in normal fibroblasts after stimulation with tumor-derived inflammatory cytokines TNF-α and IL-6 and further drove the transformation of the cells into CAFs." (PMID 37821959, 2023). "Within the microenvironment of solid tumors, such as GBC, various autocrine and paracrine signaling molecules enhance tumor malignancy, among them Tumor Necrosis Factor-alpha (TNFα), Vascular Endothelial Growth Factor (VEGF), and Endothelin-1 (ET-1)." (PMID 38072958, 2023). "In contrast, another genotype of TNF-α was more frequently found in the serum of patients with lip SCCs and clinical stage I and II tumours." (PMID 36980727, 2023). "IFN-Y induces polarization of TAMs, TNF-α, and lipopolysaccharide (LPS) into the M1 (classically activated/anti-tumor) macrophage phenotype and IL-4, IL-190, TGFβ1, and PGE2, into the M2 (alternatively activated/pro-tumor) macrophage phenotype." (PMID 37637998, 2023). "Notch signaling is induced by tumor-derived TNF-α in muscle and tumor tissues during osteosarcoma-induced cachexia." (PMID 37222464, 2023). "The upregulated genes were enriched in TNF-α signaling via NF-kB, hypoxia, androgen response, and mTORC1 signaling, indicating that C7 displayed strongly tumor-promoting progression under treating with enzalutamide." (PMID 37008945, 2023). "A report on lung tissue and serum demonstrates that DEN treatment increased COX-2, TNF-α, and IL-6 levels, while others have shown elevated tumor markers (e.g., carcinoembryonic antigen, CEA)." (PMID 37259369, 2023). "Tumour angiogenesis is dependent on proinflammatory cytokines, chemokines and growth factors such as MCP-1, IL-8, TNF-α and VEGF, secreted by tumour-associated macrophages (TAMs) via the activated NF-κB pathway." (PMID 36899924, 2023). "In established tumours, CD4+ TH1 TILs displayed high PD-1 expression, which was also associated with polyfunctional IFN-γ and TNF production ex vivo." (PMID 37153625, 2023). "For instance, they boosted the production of Th1 cytokines (IL-2, IFN-γ, and TNF-α), which helped to kill tumor cells through increased production of CD4+/CD8+ lymphocytes." (PMID 37047572, 2023). "In our report, the HDAC inhibitor-induced TNF-α secretion corresponded to a synergistic anti-tumor effect with SMs." (PMID 36831656, 2023). "TAN are inflammatory in the early stages of the tumor, secreting TNF-α, IL-1, and several kinds of interferons (IFNs), and immunosuppressive in the later stages, secreting TGF-β and PGE-2." (PMID 36771154, 2023). "Recent studies have also demonstrated interesting findings when investigating the potential role of TNF-α and its family proteins to predict prognosis, tumour immune characteristics, and immunotherapy response in several cancer types." (PMID 36980727, 2023). "NF-κB p65 (RelA) and TNF-α were discovered to be significantly expressed in tumor samples of various cancers through pan-cancer expression analysis." (PMID 37892820, 2023). "We measured the concentrations of inflammatory cytokines in tumor tissue 3 days after bacterial treatment and observed that the levels of inflammatory cytokines (TNF-α and IL-1β) were increased in the bacterial treatment groups." (PMID 37908720, 2023). "The proinflammatory factors tumor necrosis factor (TNF-α), IL-6, IL-10, IL-23, nitric oxide (NO) and reactive oxygen species (ROS) secreted by M1 macrophages can significantly increase the inhibition of tumor cell proliferation." (PMID 36969211, 2023).